ENSG00000263020 (novel protein)
Gene: Protein-coding gene on chromosome 6 (31,666,102 to 31,673,546, forward strand). Ensembl gene ENSG00000263020.
Genetic constraint (gnomAD): Loss-of-function variants: 10 observed, 29.88 expected, observed/expected ratio (o/e) 0.33, 90% interval 0.2 to 0.57. Missense variants: 131 observed, 292.98 expected, observed/expected ratio (o/e) 0.45, 90% interval 0.39 to 0.52. Synonymous variants: 89 observed, 102.63 expected, observed/expected ratio (o/e) 0.87, 90% interval 0.73 to 1.03.